DVL1 (dishevelled segment polarity protein 1)
Diseases named in the same sentence as DVL1 in open-access papers (continued):
Sharing a sentence is not in itself a finding about the gene and the disease.
cancer (continued). "Since K69 and K285 residues are known regulatory switches for DVL-1 nuclear localization, we wanted to determine whether these K-residues on DVL-1 also influence transcript levels of DVL-1 target genes such as TRIO, COL5A1 and EXD3 implicated in cancer." (PMID 34659647, 2021). "Because DVL-1 is implicated in tumorigenesis but remains poorly characterized, we analysed the relative mRNA and protein expression of DVL-1 in our panel of cancer cell lines." (PMID 31700102, 2019). "Not only do DVLs bind to multiple tissue-specific aromatase promoters that are aberrantly activated in cancer, but the role of DVL-1 vs. DVL-3 appears to play a promoter-specific and cell- type dependent role that can lead to either activation or repression of CYP19A1 transcripts." (PMID 30479694, 2018). "However, DVL1 has been studied in other types of cancers, suggesting its potential role in cancer biology and signaling pathways, which might be relevant for future investigations in NETs." (PMID 39796676, 2024). "Furthermore, analysis using TIMER database and gene expression studies indicates that high levels of DVL-1 are inversely correlated with target genes including infiltration of CD8+ and CD4+ T cells, highlighting a potential connection of DVL-1 in cancer immunomodulation." (PMID 34659647, 2021). "After establishing that K69 and K285 acetylation promotes DVL-1 nuclear localization, we next wanted to determine whether acetylation-dependent nuclear translocation of DVL-1 also influences its promoter binding to genes implicated in cancer." (PMID 31700102, 2019). "Not only does acetylation play an important role in DVL-1 nuclear translocation, but also appears to influence its binding to multiple aromatase promoters, as well as differentially regulates tissue-specific aromatase transcripts that are aberrantly activated in cancer." (PMID 31700102, 2019). "Indeed, deregulated Wnt pathways and the overexpression of DVL1 were reported in various cancers." (PMID 24755370, 2014). "Further clinical research is needed to validate the therapeutic potential of targeting DVL1, aiming to enhance immunotherapy effectiveness and provide more personalized treatment strategies for patients facing both SIC and cancer." (PMID 40276499, 2025). "With the continuous advancement of research, DVL1 will become a new breakthrough in the treatment of SIC and even cancer-related cardiovascular diseases, contributing to the development of new treatment methods." (PMID 40276499, 2025). "Collectively, these findings suggest that while DVL1 expression remains consistent across COAD stages, its dependency and functional interactions highlight its critical role in cancer biology, particularly in cell survival and proliferation pathways." (PMID 40276499, 2025). "DVL1 is a core regulator of SIC and other cancers and, therefore, can serve as a therapeutic target." (PMID 40276499, 2025). "For a more comprehensive analysis of DVL nuclear function, we screened for novel DVL-1 target genes and discovered that DVL-1 binds to various genes involved in cancer biology and T-cell mediated immunity in TNBC models." (PMID 34659647, 2021). "In contrast to WWOX and DVL2, expression rates of DVL1 and DVL3 were higher in cancer cell lines compared to normal 26-28." (PMID 32368285, 2020). "We also wanted to determine DVL-1 acetylation status in a non-cancer setting, and therefore, we performed LC-MS/MS in MCF10A cells and surprisingly our results show that endogenous DVL-1 is acetylated in K34, K69, K438, and K476 in this cell line." (PMID 31700102, 2019). "The combined results from transcriptomic analyses, drug susceptibility screening, and spatial transcriptomics provide a comprehensive view of DVL1’s involvement in both SIC and cancer, positioning Digoxin as a promising therapeutic strategy for regulating these pathways." (PMID 40276499, 2025).
cancer (continued). "Especially in cancer patients, the impact of SIC on cardiac function may be more severe, and thus DVL1-targeted therapies may be an important complement to personalised immunotherapy." (PMID 40276499, 2025). "The DVL-1 and DVL-3 proteins also play an important role in cancer chemoresistance." (PMID 35267666, 2022). "Moreover, FUBP1 expression increased in several types of cancers, further exploring the role of FUBP1 and DVL1 on stemness transformation and metastasis in those cancers will broaden its significance." (PMID 34288405, 2021). "Thus, negative modulators of DVL1 are able to impair the binding to Frizzled receptors, turning off the aberrant activation of the WNT pathway and leading to anti-cancer activity." (PMID 35267666, 2022).
infection (3 papers, 2014 to 2021). The state of being infected such as from the introduction of a foreign agent such as serum, vaccine, antigenic substance or organism. "Loss of intracellular signal relay protein Dvl1 significantly reduced infection, while Dvl2 knockdown did not, suggesting redundant mechanisms are at play at this level of the signaling cascade." (PMID 33883266, 2021). "To test whether PCP pathway components are involved in A–P guidance of corticospinal axons, we designed and packaged short hairpin RNA (shRNA)-expressing lentivirus targeting Ryk, Vangl2, Fzd3 or Dvl1 for in vitro infection studies." (PMID 28660073, 2017).
kidney disease (2 papers, 2021 to 2023). "One discovered DAS gene (DVL1) was a component of the Wnt signaling in kidney disease." (PMID 38074096, 2023). "As far as we are aware, this is a first study that had shown expression and localization of α-tubulin along with inversin and DVL-1 in fetal and postnatal human kidneys, and that had explored the expression of mentioned proteins in kidney diseases, such as MCDK, FSGS and CNF." (PMID 33800671, 2021). "Furthermore, we wanted to explore whether the expression and staining pattern of α-tubulin, inversin and DVL-1 is disturbed in different kidney diseases when compared to healthy control." (PMID 33800671, 2021).
mental illnesses (2 papers, 2013). "For example, Dvl1 mutants, which provide a model of several human psychiatric disorders, show impairment in nesting building behaviours as well as reduced social interactions and abnormal PPI." (PMID 23840597, 2013).
gastrointestinal tumors (1 paper, 2025). "Supplementary analyses extended these findings to gastrointestinal tumors, where DVL1 was linked to poor prognosis and altered immune landscapes, reinforcing its role as a critical gene across multiple conditions." (PMID 40276499, 2025).
inflammation (1 paper, 2025). Aberrant reaction of the microcirculation characterized by movement of fluid and leukocytes from the blood into extravascular tissues. "Although there is no direct evidence linking DVL-1 to synovial inflammation in OA, its role in RA, where it supports the survival of fibroblast-like synoviocytes (FLS), suggests a potential indirect influence on the inflammatory processes within OA joints." (PMID 40299569, 2025).
DVL1 also shares sentences with these, for which no sentence is quoted: breast (2 papers); colorectal adenocarcinoma (2); lung squamous cell carcinoma (2); melanoma (2); mesothelioma (2); acute myeloid leukemia (1); adenocarcinoma (1); anaplastic astrocytoma (1); aortic stenosis (1); Brachycephaly (1); breast disease (1); candidiasis (1); cardiovascular diseases (1); Carpenter syndrome (1); cervical squamous cell carcinoma (1); chordoma (1); chronic kidney failure (1); chronic lymphocytic leukemia (1); cleft palate (1); colon adenocarcinoma (1); cryptococcosis (1); cystic kidney disease (1); diffuse astrocytoma (1); dysplasia (1); embryonic carcinoma (1); epilepsy (1); focal segmental glomerulosclerosis (1); Gardner syndrome (1); gastric cancer (1); Hirschsprung disease (1).
A further 21 diseases each share a sentence with DVL1 in 1 paper.